CD44 (CD44 molecule (IN blood group))
Diseases named in the same sentence as CD44 in open-access papers (continued):
Sharing a sentence is not in itself a finding about the gene and the disease.
glioblastoma (continued). "Glioblastoma cells forming aggregates, as well as undifferentiated GFAP+NNP, co-expressed SOX-2, Nestin, Beta III-tubulin, MAP2, GFAP, Vimentin, Fibronectin and CD44, when cultured under serum-starvation media." (PMID 19216795, 2009). "Notably, the LSPR sensor successfully detected elevated levels of CD44 and CD133 in blood and CSF from a glioblastoma mouse model, highlighting its clinical potential for minimally invasive, multi-biomarker liquid biopsy diagnostics in GBM monitoring." (PMID 40801693, 2025). "However, there has been no study of the relative expression and prognostic significance of all members of the HER family with EGFRvIII, CD44, and CD109 in patients with glioblastoma." (PMID 40227788, 2025). "The overexpression of CD44 has been reported in many studies but not so much for CD109 in glioblastoma patients." (PMID 40227788, 2025). "The glioblastoma antigens currently targeted in the clinic, often in combination, are Cluster of Differentiation proteins (CD133, CD44 & CD70), IL receptors (IL-13Ra2), EGFR and EGFRvIII, ephrin receptor A2 (EphA2), human epidermal growth factor receptor 2 (HER2) and B7-H3." (PMID 41208963, 2025). "It is also possible that the PDX lines do not use CD44 as a clutch, however previous findings strongly suggest a role of CD44 in glioblastoma migration." (PMID 38737451, 2024). "Further in silico analysis of TIMER2 glioblastoma patient data sets also suggested that RCN3 showed a positive correlation with stemness marker CD44 and a negative correlation with differentiation markers such as ID4, MAP2, and NTRK5." (PMID 37046668, 2023). "Moreover, CD44 was found to be expressed in malignant mesenchymal GSC (Mes‐GSC) and served as a Mes‐GSC marker during glioblastoma metastasis." (PMID 37062068, 2023). "Importantly, we found a correlation between the expression of stemness markers (CD44 and FUT4 (CD15)) with ABCC3 in glioblastoma." (PMID 36585418, 2022). "RFX1 performs its function by binding with ectodomain of CD44 and downregulates CD44 expression resulting in reduced phosphorylation of Erk and Akt, thus have negative effect on glioblastoma progression and invasion." (PMID 36185622, 2022). "Displacement of CD44 from lipid rafts to non-raft membrane regions allows for CD44 shedding by the metallopeptidase ADAM10 which induces human glioblastoma cell migration." (PMID 36439249, 2022). "Similarly, in TGFβ-treated glioblastoma U251MG cell cultures, the CD44 TM-ICD and CD44 ICD products were clearly detected in TGFβ-stimulated cultures after the inhibition of lysosomal or proteasomal degradation." (PMID 33804427, 2021). "The levels of 15 microRNAs in EVs that were separated by size-exclusion chromatography were studied by quantitative real-time PCR, followed by CD44 immunoprecipitation (SEC + CD44), and compared with those from the total serum of glioblastoma patients (n = 55) and healthy volunteers (n = 10)." (PMID 33003586, 2020). "In an attempt to classify glioblastoma tumors into proneural and mesenchymal subtypes, we performed IHC on 38 glioblastoma samples with markers such as OLIG2, PDGFR-α for the proneural and CD44, YKL-40 for the mesenchymal subtype." (PMID 28744448, 2017). "In addition, we also identified key genes, including MMP9, CD44, CDC42, COL1A1, COL1A2, CAMK2A, and CAMK2B, as potential target genes for diagnosing glioblastoma." (PMID 28191466, 2017). "Additionally, we analyzed the mRNA level of CD133, CD44, CD15 and CD49f, which have been used as markers for glioblastoma TICs5." (PMID 27549983, 2016). "In GBM, overexpressing METTL3 reduces CD44 expression and sphere-formation rate of glioblastoma stem cells (GSCs), indicating that it suppresses GSC growth and self-renewal, whose presence confers cell resistance to radiotherapy and chemotherapy." (PMID 35864970, 2022). "In glioblastoma, MSN could increase CD44 expression driven by the Wnt/β-catenin signaling pathway." (PMID 35332109, 2022).
glioblastoma (continued). "Similarly, the expression of mesenchymal subtype markers, such as FN, Vim, and YKL-40 (a marker for the mesenchymal subtype of glioblastoma, also known as Chitinase-3-like protein 1, CHI3L1), was induced by irradiation and suppressed by blocking CD44 expression." (PMID 34681583, 2021). "In GBM cells, Id1 is also a potential downstream effector of protein tyrosine kinase 7(PTK7) and transglutaminase 2 (TGM2) which are highly expressed in CD44-high glioblastoma and predicts unfavorable prognosis." (PMID 32410828, 2020). "Therefore, if CD44 inactivation inhibits EMT, it could prevent the formation and progression of glioblastoma and provide a potential option for glioblastoma treatment." (PMID 31528214, 2019). "However, their overexpression was observed to repress the cell proliferation and migration, and invasion of GBM through downregulating the IGF2BP1 levels, which reduces the level of c-MYC, CD44, MKI67, and PTEN mRNA in GBM cells or blocks G1/S transition in glioblastoma cell." (PMID 29954406, 2018). "The hyaluronan receptor CD44 has an important role in glioblastoma multiforme (GBM) progression, but the precise mechanisms have not been elucidated." (PMID 35954411, 2022). "Inhibition of the interaction between HA and CD44 reduces glioblastoma invasion in hydrogels lacking matrix-bound HA, suggesting of production of HA in GBM cells." (PMID 34149360, 2021). "Hence, CD44+/CD133+/ITGA6+/CD36+ is the core signature that is consistently present in all seven gliomasphere systems as the common consensus multi‐marker combination – irrespective of the origin of the gliomasphere (stem‐like cell line, traditional glioblastoma cell line or patient‐derived)." (PMID 30467961, 2019). "The four anti-CD44 mAbs, produced by the four hybridomas, P4G9, P3D2, P3A7 and P3G4, stained fixed cells of three different tumorigenic cell lines(breast, melanoma, glioblastoma) and a nontumorigenic breast cell line." (PMID 33891595, 2021). "Recent evidence revealed that overexpression of miR-373 in glioblastoma cells did not affect the cell growth but suppressed migration and invasion by inhibiting the expression of CD44 and TGFBR2, suggesting that CD44 can be directly targeted by miR-373." (PMID 32429463, 2020). "The glioblastoma masses with low or no expression of CD133 could develop adhesive properties and express CD44 as a stemness marker." (PMID 39513861, 2024).
melanoma (226 papers, 2007 to 2026). A malignant, usually aggressive tumor composed of atypical, neoplastic melanocytes. "Training on DCs impacted the functional shape of CD8 T cells infiltrating melanoma tumors, which displayed the expression of Ki67 and Granzyme B, associated with a higher expression of CD44, suggesting that these cells acquired a memory phenotype." (PMID 38812523, 2024). "U2AF2 knockdown and overexpression experiments revealed its positive regulatory role in the inclusion of variant exons and CD44 isoform 3 expression in melanoma cells." (PMID 38106992, 2023). "For example, CD44 Splice Variant V8–V10 (CD44V8–V10) overexpression in the metastatic melanoma line Lu1205 induces junction disassembly and VE‐cadherin phosphorylation in ECs." (PMID 36807637, 2023). "B16-CD46 cells are PD-L1+ and express high levels of the adhesion molecules CD61 and CD44, which are both implicated in the metastatic process of B16 melanoma." (PMID 35141399, 2022). "High CD44 surface expression in primary melanoma correlates with increased metastatic risk and reduced survival." (PMID 34680442, 2021). "CD44 expression is associated with poor prognosis of melanoma, and different studies have shown that binding of collagen I or HA to CD44 promote tumor progression." (PMID 32984031, 2020). "While MT1-MMP can cleave CD44 and has been implicated for constitutive shedding of CD44 from the human melanoma cell surface, ADAM-10, MMP-9, and a chymotrypsin-like enzyme have also been described as CD44 sheddases." (PMID 31137480, 2019). "This is in line with the association of CD44 overexpression with tumor progression and metastasis in various human cancers including melanoma." (PMID 31741714, 2019). "Melanoma cell administration caused massive lung metastasis in WT mice whereas this metastatic response was markedly decreased in lungs from CD44−/− mice." (PMID 30165890, 2018). "Coordinate expression of Id1 or Id3 or CD44 with HAS2 or HAS3 or CD44 was found to be associated with reduced survival of human melanoma patients." (PMID 30297743, 2018). "As the cytoplasmic portion of CD44 interacts with Smad1 in chondrocytes, and promotes phosphorylation of Smad1 and Smad4 and their nuclear translocation, it is likely that a similar mechanism underlies the BMPR co-receptor function for CD44 in melanoma cells." (PMID 30297743, 2018). "These nanoparticles were shown to efficiently accumulate in the CD44-overexpressing murine melanoma tumor tissues and the cross-linked siRNAs had 50% more stability than the uncross-linked siRNAs." (PMID 25954275, 2015). "As a surrogate for representation of all of the expressed alternative splice variants of CD44, we developed a method to determine a ‘fingerprint’ of expression in human melanoma." (PMID 23342032, 2013). "In addition, markers typically associated with MSC-derived vesicles, including CD29 (integrin β1), CD44 (hyaluronic acid receptor), CD49e (integrin α5), and melanoma-associated chondroitin sulfate proteoglycan (MCSP), were robustly detected." (PMID 41410757, 2025). "It was shown that introduction of cDNA encoding a soluble form of CD44 into melanoma cells of line 1F6 inhibited their growth by competitively blocking the binding of CD44 on the cell surface to hyaluronic acid, which was confirmed experimentally under in vitro and in vivo conditions." (PMID 39594665, 2024). "In the case of melanoma, CD44 has been implicated in cell migration and proliferation in vitro." (PMID 36077992, 2022). "Among CD44 variants, the CD44v3 splice is associated with metastasis in melanoma patients." (PMID 34207884, 2021). "Investigation of the molecular mechanisms underlying the mambalgin-2 activity in metastatic melanoma cells and their adaptation to the cell media acidification revealed that incubation of mel P cells with mambalgin-2 leads to the down-regulation of CD44 and Frizzled 4 cell-surface expression." (PMID 34680442, 2021).
melanoma (continued). "However, in B16 melanoma invasive variants, expression of motility receptors like β1 integrin and CD44 remains unaltered." (PMID 25180193, 2014). "As CD44 has multifaceted role in the hyaluronan metabolism acting both in ligation of hyaluronan on the cell surface and in its endocytosis, the significance of its loss for hyaluronan metabolism in melanoma is somewhat difficult to deduce." (PMID 23560496, 2013). "Similarly, the levels of hyaluronan and its receptor CD44 are reduced in clinical stage I melanomas associating with poor patient prognosis." (PMID 23560496, 2013). "In addition, a screen of 51 monoclonal antibodies against cell surface molecules identified two mAbs that blocked coalescence in the 3D Matrigel model, one against beta-1-integrin (CD29), and one against CD44, the hyaluronate adhesion receptor implicated in melanoma metastasis." (PMID 28264026, 2017). "Therefore, resveratrol might induce the differential expression of CD44 variants in melanoma cells, ECs, LAK, Treg, and MDSCs that contributes to the differential role of resveratrol and MDSC in EC protection and tumor killing." (PMID 22532866, 2012). "In melanoma, CD44 contributes to tumor invasion, metastasis, and resistance to therapy by promoting epithelial-to-mesenchymal transition (EMT) and enhancing cell survival under stress conditions." (PMID 40867277, 2025). "Weaker CD44 signals were detected in the cytoplasm of all cells, with a slight increase in intracellular localisation in melanoma cells following PACAP treatment." (PMID 41465475, 2025). "In the current study, nanoplexes having silencer CD44 siRNA, which performs as a model therapeutic drug, have shown high knockdown (>90%) in different mammalian cell lines (melanoma cell line, MV3; and retinal pigment epithelial cell line, ARPE-19)." (PMID 38998694, 2024). "The efficacy of RG7356 has been investigated by Menke-van der Houven van Oordt and colleagues in a first-in-human phase I trial in patients with locally advanced or metastatic cancers expressing high levels of CD44, including melanoma." (PMID 39199632, 2024). "In the anti-PD-1-melanoma cohort (GSE91061), CD44 up-regulation was associated with low response to PD-1 treatment." (PMID 38590654, 2024). "In melanoma cells, soluble CD44 acts as a competitor of CD44 and blocks HA‐CD44 interaction, thereby inhibiting tumor growth and metastasis." (PMID 37953485, 2024). "B16-F10 melanoma cells that constitutively expressed CD44 showed significant adhesion to HA-coated plates, and this adhesion was almost completely blocked by neutralizing antibodies against either CD44 or Pep-1." (PMID 39594665, 2024). "CD44 interacts with components of the extracellular matrix, such as hyaluronic acid, facilitating not only migration but also invasion of melanoma cells." (PMID 39518076, 2024). "In contrast, when melanoma cells pretreated with CD44 blocking antibodies were mixed before MEKi treatment with either differentiated TTR or naive macrophages, CD44 blockade was able to reverse TTR macrophage-mediated protection of MEKi-induced cell death." (PMID 38942020, 2024). "Compelling evidence suggests that drugs targeting CD44 in melanoma is a promising strategy for melanoma treatment." (PMID 38783892, 2024). "Short peptides with the HA-binding motif BX7B in RHAMM and CD44 have been shown to inhibit melanoma growth and induce apoptosis." (PMID 38791985, 2024). "In our study, the tumor cell protection ability of POSTN-polarized TTR macrophages was greatly suppressed in the presence of CD44-neutralizing antibodies, demonstrating a role for this pathway in targeted therapy resistance formation in melanoma." (PMID 38942020, 2024). "It has been reported that upstream genes can regulate the level of CD44 protein in melanoma through promoting the ubiquitination and degradation of CD44." (PMID 38627379, 2024).
melanoma (continued). "In cell monolayers (2D model) the cisPt/NaHA complex in solution demonstrated dose- and time-dependent cytotoxic effect by decreasing the viability of pancreatic, melanoma, and lung cell lines (they all express CD44)." (PMID 37958708, 2023). "In this regard, Chen and team came up with hyaluronan (HA, 49 kDa) attached cationic bovine serum albumin (BSA) NPs loaded with PTX for CD44 targeted melanoma therapy." (PMID 36635761, 2023). "Exosomes from melanoma CSCs express the CD44 CSC-related marker, and this expression was reduced after treatment." (PMID 37509327, 2023). "For example, the presence of HA chemical clues to melanoma cells (e.g., cell surface receptors, such as CD44, which is the principal HA receptor on melanoma cells) and increased concentration can modulate tumor progression and poor survival rates in melanoma." (PMID 37888160, 2023). "A previous study showed that downregulation of RNF128 induced EMT and stemness in melanoma cells through CD44 and CTTN ubiquitination." (PMID 37383713, 2023). "HA enhances signaling affecting melanoma cell motility through CD44/EGFR interaction, and the FAK activation and ROS-dependent production of MMP-2." (PMID 37107200, 2023). "Silencing of ESRP1 significantly decreased the expression of CD44 isoforms containing exon v6 in human MB and LH cells derived from melanoma lymph node metastases." (PMID 38106992, 2023). "In patients with melanoma, low RNF128 expression levels and high CD44 levels are associated with a poor prognosis." (PMID 36605595, 2022). "After 5 days in low attachment and serum-free medium conditions, melanoma stem-like subsets (i.e., spheres) showed high levels of CD44 expression, similar to that of the parental cells." (PMID 35847038, 2022). "CD44 is recognized as a cancer stem cell marker in canine breast tumors, and its expression is also increased in canine leukemia, melanoma, and osteosarcoma." (PMID 36077992, 2022). "Down‐regulation of NRF2 in melanoma led to an epithelial mesenchymal transition phenotype and an up‐regulation of the stem cell marker CD44." (PMID 34951143, 2022). "Reductive-responsive paclitaxel (PTX)-loaded HA-ss-TOS-PTX was efficiently taken up by CD44-induced endocytosis on CD44 overexpressing B16F10 melanoma cells, and exhibited enhanced cytotoxicity." (PMID 36559325, 2022). "Future approaches to inhibit NRF2 in melanoma should be combined with CD44 targeting and thus improve efficacy and clinical outcome." (PMID 34951143, 2022). "Then, taking degree >8 as the screening index, we selected 19 genes, of which the CD44 gene had low expression and the other genes had high expression in melanoma." (PMID 33854593, 2021). "The results of double labeling of Sox10 with CD44 (melanoma stem cell marker) revealed that specific nucleus Sox10 expressed in melanocyte stem cell within the bulge (a1-b4), anagen hair bulb (b5-b7) and epithelial strand in catagen (c1-c4)." (PMID 34522176, 2021). "CD44 interaction with MMP-9 on the cell surface of melanoma cells promotes the degradation of collagen IV and cell invasion." (PMID 33505471, 2021). "The cell-surface hyaluronan receptor, CD44, binds to MMP9 on melanoma cells and forms a CD44/MMP9 complex." (PMID 34207884, 2021). "Recent work demonstrated that the direct correlation of the CD44–HA interaction on proliferation and invasiveness of melanoma cell lines is dependent on the molecular weight and the presentation form (matrix-bound or soluble) of HA." (PMID 34944493, 2021). "A previous study reported that soluble CD44 inhibits the growth of melanoma tumors by blocking cell surface CD44 binding to hyaluronic acid." (PMID 33540700, 2021). "Mechanistically, this has been attributed to the interaction of Gal-9 with CD44, whereby metastatic spread was hampered, and the number of lung metastases was reduced in a melanoma mouse model." (PMID 35052746, 2021).